EGFR (epidermal growth factor receptor)
Diseases named in the same sentence as EGFR in open-access papers (continued):
Sharing a sentence is not in itself a finding about the gene and the disease.
cancer (continued). "The median survival for exon 20 insertion patients was 16 months, comparable to wild-type cancers but shorter than in cancers with common EGFR mutations." (PMID 40136378, 2025). "In conclusion, our research offers novel insights into EGFR linked to immunotherapy response and prognosis in pan-cancer." (PMID 40574864, 2025). "Univariable analysis showed that shorter time-to-treatment discontinuation was associated with socioeconomic deprivation, EGFR L858R mutations, distant disease at cancer diagnosis, and adenocarcinoma morphology." (PMID 40029742, 2025). "Our study demonstrated that TARG1 deficiency significantly reduced EGFR expression, a key proto-oncogene involved in cancer-related processes such as migration, proliferation, and adhesion." (PMID 40603466, 2025). "Some point towards its important role as a cancer-promoting OncomiR associated with ErbB2 and EGFR expression upregulation, Wnt signaling upregulation, and collagen type I deposition regulation, all associated with bone metastasis." (PMID 40805149, 2025). "The constitutive activation of mutated EGFR in cancer stimulates glucose uptake and lactate production." (PMID 39433211, 2025). "Among its identified metabolites, Cryptotanshinone demonstrated strong binding affinity and structural stability toward multiple cancer-associated protein targets, showing binding efficacy comparable to the clinically approved EGFR inhibitor Erlotinib." (PMID 41455835, 2025). "HNSCC tumors are associated with high expression of EGFR in up to 80–90% of patients, some of the highest rates amongst all cancers." (PMID 40868227, 2025). "Next, we analysed the hallmark pathways associated with EGFR.Sig in the TCGA pan-cancer dataset by calculating Spearman correlation coefficients between EGFR.Sig expression and the enrichment scores (obtained by ssGSEA calculations) of each hallmark pathway." (PMID 40574864, 2025). "Supporting this connection are findings of abnormal expression levels of EGFR and its activation, often by mutation, in many human cancers, including those of the breast, lung, ovary, and colon." (PMID 40649937, 2025). "Some pyrimidine derivatives have been designed to selectively inhibit mutated forms of the epidermal growth factor receptor (EGFR), which are often implicated in cancer progression." (PMID 41463008, 2025). "In cancer, serum EGFRvIII constitutes active abnormal variants of the epidermal growth factor receptor (EGFR)." (PMID 41303767, 2025). "Restricting the Rheb-GEF function is an effective strategy to suppress the growth of cancer cells harboring oncogenic EGFR mutations." (PMID 40259053, 2025). "EGFR, a receptor tyrosine kinase, is frequently overexpressed or mutated in cancers, activating downstream signaling pathways that promote uncontrolled proliferation, survival, and migration." (PMID 40526618, 2025). "For EGFR mutation detection in cancer tissue, slide‐level performance after aggregation reached an accuracy of 76.67% with specificity of 80.77%, sensitivity of 73.53%, an F1 score of 78.12%, a consistency of 0.5583 of Cohen's Kappa and an AUC of 0.77." (PMID 40965349, 2025). "Increased nuclear EGFR expression has been associated with poor clinical outcomes in various cancers." (PMID 39780275, 2025). "ADAM9, a member of the A disintegrin and metalloproteinase (ADAM) family, facilitates the release of growth factors and was implicated in activating the EGFR-mediated progression in several cancer types." (PMID 40429751, 2025). "CGA has been linked to various hormone-related pathways implicated in cancer progression, including those involving EGFR and other oncogenic signaling cascades such as ERK 1/2 and Akt signaling." (PMID 39849491, 2025).
cancer (continued). "It should be emphasized that an EGFR C797S point mutation has the potential to result in the development of resistance in cancer patients treated with osimertinib." (PMID 39942770, 2025). "Numerous EGFR mutations (e.g., exon 19 deletion or L858R mutation) are constitutively active and they drive “addictive” oncogenic signaling in cancer cells." (PMID 40346640, 2025). "In the context of ATC, mutations in EGFR can abnormally activate the receptor signaling pathway, resulting in increased proliferation and resistance to apoptosis of cancer cells." (PMID 39744583, 2025). "Mutations in EPS15 have been shown to be associated with cancers with abnormalities in the EGFR pathway." (PMID 40678018, 2025). "Epidermal growth factor receptor inhibitors (EGFRIs) are used to treat certain cancers but frequently cause cutaneous inflammation that can hinder treatment." (PMID 39924511, 2025). "Recognizing the critical role of ADAM9 as a protease with oncogenic effects in cancer progression, particularly through EGFR activation in various cancers, including LUAD, we investigated polymorphisms located on promoter and intron regions of the ADAM9 gene." (PMID 40429751, 2025). "In our study, EGFR emerges within meta-signatures linked to autophagy and hypoxia, patterns observed in the literature for other cancers, such as lung cancer." (PMID 39796763, 2025). "The epidermal growth factor receptor (EGFR) plays a crucial role in inhibiting cancer cell growth and serves as a key target for treatment, particularly in malignancies characterised by EGFR overexpression or mutations." (PMID 40265416, 2025). "EGFR has a variety of associated drugs which have been previously used in phase IV clinical trials to treat several different cancers." (PMID 39565278, 2025). "A previous report identified osimertinib as an effective treatment for pleomorphic carcinomas harboring EGFR mutations with exon 19 deletions." (PMID 40104449, 2025). "Abnormal activation of the EGFR pathway has been reported to be associated with chemoresistance in many types of cancer." (PMID 38960034, 2024). "Overexpression of Trefoil factor 1 is involved in pathways, including Rho-GTPases, Rho-kinase, PI3-kinase, PLC, and COX-2 and they interact with other receptor systems to activate epidermal growth factor receptor EGFR indirectly causing progression of cancer." (PMID 39839775, 2024). "In summary, our findings suggest that PCs reduce the sensitivity of EGFR‐mutated cancer cells to TKI treatment through paracrine signaling." (PMID 39435643, 2024). "Recent findings also implicated YAP in drug tolerance and the induction of cancer dormancy in EGFR-mutant NSCLC10." (PMID 38702301, 2024). "Key targeted therapies include RET inhibitors like selpercatinib for RET rearrangements, ALK inhibitors like alectinib and crizotinib for ALK gene alterations, and EGFR inhibitors like osimertinib and erlotinib for EGFR-mutated cancers." (PMID 39457373, 2024). "This variation is influenced by factors, such as the histological type of the cancer, the status of the epidermal growth factor receptor (EGFR) mutation, and the stage of the disease." (PMID 38502313, 2024). "Further RT‐PCR analysis consistently indicated that IL32 was the only cytokine consistently up‐regulated in PCs when compared to EGFR‐mutated cancer cell lines or their paired primary cancer cells." (PMID 39435643, 2024). "EGFR mutations or amplifications are frequently associated with the progression of cancer and an unfavorable prognosis." (PMID 38613804, 2024). "Clinically available EGFR-targeting therapies are more beneficial for cancer patients with EGFR mutations; whereas, for most CRC patients with wild-type EGFR, these treatment modalities are blunted." (PMID 38263401, 2024). "An abnormal overexpression or mutation of EGFR in malignant tumors confers significant proliferative and angiogenic advantages to cancer cells." (PMID 39519855, 2024).
cancer (continued). "In summary, second-generation TKIs like afatinib represent a significant advancement in targeted cancer therapy by overcoming resistance mechanisms associated with the T790M mutation and offering more potent inhibition of the EGFR." (PMID 39337496, 2024). "In contrast to normal cells, cancer cells often display overexpression of EGFR or amplifications of genes encoding growth factor receptors." (PMID 38791037, 2024). "The EGFR mutation in non-small-cell lung cancer (NSCLC) is one of earliest recognized driver gene mutations in the treatment of cancers." (PMID 39272824, 2024). "In pursuit of this goal, researchers are designing and synthesizing novel chemical structures targeting key biological pathways implicated in cancer progression, such as EGFR, CDKs, Ras, and tubulin proteins." (PMID 39404419, 2024). "The exploration of anti-MET antibody drugs for NSCLC is a promising field in targeted cancer therapy, especially in overcoming resistance mechanisms associated with EGFR mutations." (PMID 39449330, 2024). "EGFR overexpression has been implicated in several types of cancer such as colorectal, breast, ovarian, pancreatic, bladder, and HNSCC." (PMID 39239273, 2024). "Using multiple cell lines and animal models, we demonstrated that loss-of-function changes of ZNRF3/RNF43 elevate EGFR signaling activity to promote cancer progression." (PMID 38260423, 2024). "For instance, PD-L1+ sEV potential was investigated in different cancers alone, and its combination with other biomarkers (e.g. ctDNA) was used to improve the identification of EGFR mutations in lung cancer." (PMID 37973956, 2024). "The IC50 results indicated that the addition of IL32 increased the IC50 value of TKI drugs in EGFR‐mutated cancer cells treated with CM from YY1‐depleted PCs compared to the placebo‐treated group." (PMID 39435643, 2024). "Multiple receptors involved in signaling pathways implicated in cancer progression, such as EGFR, TrkA, and TOLL-like receptors, are associated with NEU1." (PMID 39194692, 2024). "While EGFR itself is a critical target in cancer therapy due to its overexpression and mutations in various tumors, it is essential to recognize that the downstream signaling pathways activated by EGFR are the primary drivers of cancer progression." (PMID 39126121, 2024). "EGFR mutations function as a faulty switch that triggers aberrant cellular signaling, promoting uncontrolled cancer growth." (PMID 38910714, 2024). "High EGFR expression is associated with poorer prognosis and reduced survival, as indicated by the significant correlation with cancer-specific survival." (PMID 39594688, 2024). "High prevalence of EGFR mutations, with detection of these in 85% of patients, was revealed by genomic profiling of genes involved in oncogenesis according to the Cancer Gene Census (COSMIC)." (PMID 38539567, 2024). "Most of these cancers exhibit a biologically simple cancer network, often characterized by a single predominant oncogenic driver, such as an EGFR or ALK mutation." (PMID 39300154, 2024). "EGFR, particularly ErbB2, mutates in several epithelial tumors and clinical investigations showed that they contributed to the development of cancer." (PMID 38686058, 2024). "The result of KRAS mutation-positive A549 cells treated with BI-4020 suggested that driver mutation-positive cancers other than EGFR would be insensitive to BI-4020." (PMID 38396251, 2024). "Multiple studies have demonstrated that ncRNAs can impact the efficacy of osimertinib treatment in NSCLC with EGFR mutations by regulating cancer cell apoptosis and pyroptosis, either individually or in combination." (PMID 39324002, 2024). "Considering the limitations of immunotherapy in treating NSCLC individuals harboring EGFR mutations, EGFR‐TKIs remain the preferred treatment modality for individuals with this cancer type." (PMID 38659399, 2024).
cancer (continued). "This strategy has seen success with mAbs designed to bind to surface molecules associated with cancer, including the epidermal growth factor receptor (EGFR), human epidermal growth factor receptor 2 (HER2), and CD20." (PMID 39590377, 2024). "In summary, our findings indicate that pericyte‐derived IL32 activates the β5‐integrin mediated Src‐Akt signaling pathway, thereby negating the inhibitory effects of TKIs on this pathway in EGFR‐mutated cancer cells." (PMID 39435643, 2024). "They found that targeting DUSP6 reduced cell viability due to unleashing the excessive and toxic levels of RAS-mediated ERK activity in cancer cells harboring mutations in EGFR and KRAS201." (PMID 38485987, 2024). "Epidermal growth factor receptor (EGFR) is a receptor that is overexpressed or mutated in various types of cancer, making it an attractive target for therapeutic interventions." (PMID 38605072, 2024). "In summary, this comprehensive screen expands the landscape of functional EGFR variants and suggests broader clinical investigation of EGFR inhibition for cancers harboring extracellular domain mutations." (PMID 38548752, 2024). "Aberrant activation of the mitogen-activated protein kinase (MAPK) signaling cascade, occurring in over 85% of cancers, is mainly caused by the genetic alterations of its main components—oncogenes EGFR and RAS, and plays a crucial role in cell fate." (PMID 38374954, 2024). "Crosstalk between the MET and EGFR pathways, involving cell survival, proliferation, and migration, has been implicated in the development and progression of cancer in certain tissues." (PMID 38654922, 2024). "As the cancer progressed, ctDNA analysis showed the appearance of an epidermal growth factor (EGFR) mutation in the plasma samples." (PMID 39272653, 2024). "The association between EGFR immunoexpression and the degree of malignancy is also consistent with previous studies on several canine cancer." (PMID 38248333, 2024). "Consistent with previous reports, canonical cancer gene mutations in EGFR, ERBB2, and BRAF were always truncal as early as the AAH/AIS stage, suggesting that these mutations are very early genomic events before the acquisition of invasiveness." (PMID 38764572, 2024). "EGFR mutation increases the risk of cancer recurrence in patients with NSCLC and can also be used as an indicator to determine treatment strategies." (PMID 38195717, 2024). "Among patients with EGFR-positive NSQ cancer, exon-19 deletion variants occurred in almost half of patients, followed by exon-21 L858R substitution." (PMID 38334998, 2024). "After validating the models, AutoPepVax was applied to a list of prevalent EGFR missense mutations in four different cancers." (PMID 38675381, 2024). "This assay can identify various genetic mutations, including EGFR exon 19 deletions and EGFR exon 21 L858R alterations, from cfDNA found in the plasma of cancer patients." (PMID 39239557, 2024). "Consider cancer cells with METex14 and one of resistance mutation R1 (EGFR, HER2, RET, ALK, FGFR, K-RAS) that substitute for MET." (PMID 38188499, 2024). "The therapeutic targets of “QN” agarwood for the treatment of DKD predominantly focus on pathways associated with cancer, EGFR tyrosine kinase inhibitor resistance, and the HIF-1 signaling pathway." (PMID 38654354, 2024). "This study investigates how pericytes regulate the sensitivity of EGFR‐mutated cancer cells to tyrosine kinase inhibitors (TKIs)." (PMID 39435643, 2024). "Together, these data support further investigations into dacomitinib sensitivity in cancers harboring EGFR ECD mutations." (PMID 38548752, 2024). "Mutations in EGFR have been associated with multiple cancer histologies and are an important target of anti-cancer therapies, most commonly in lung adenocarcinoma." (PMID 39057170, 2024). "The purpose of EGFR-targeted therapy is to detect EGFR-positive cancers and existent mutations and to combat frequently acquired drug resistance." (PMID 39273318, 2024).
cancer (continued). "Our this study suggests a new mechanism of HSP70 inhibition to block DNA replication and induce DNA replication stress in certain types of human cancer cells, including EGFR-mutated cancer cells." (PMID 39470734, 2024). "Acquisition of new mutations or pre-existing genetic alterations is linked to disease progression in NSCLC patients with EGFR mutations, and the highly heterogeneous and complex genetic landscape of this type of cancer impacts clinical outcomes." (PMID 39497713, 2024). "We applied AutoPepVax to the design of the first pan-cancer vaccine design to target EGFR, and our results indicate that the EGFR missense mutations for each cancer contain immunogenic peptides." (PMID 38675381, 2024). "The cancer-promoting capacity of cancer-associated fibroblasts was facilitated by modifying EGFR core fucosylation in non-small cell lung cancer." (PMID 38561745, 2024). "Less than 5% of head and neck cancers present EGFR mutations, making this cancer type particularly difficult to treat." (PMID 39273318, 2024). "In this study, we established two models based on cfDNA coverage patterns at the transcription start sites (TSSs) from 6X whole-genome sequencing: an Early Cancer Screening Model and an EGFR mutation status prediction model." (PMID 38927119, 2024). "Patients with high levels of nuclear EGFR in cancer often presented poorer clinical outcomes, associated with resistance to cetuximab and gefitinib." (PMID 39404930, 2024). "In summary, elevated levels of nuclear EGFR are associated with inferior clinical outcomes in certain cancer types." (PMID 39404930, 2024). "Conversely, the effectors, such as EGFR, which are more upstream and have a wider array of targets belonging to distinctive pathways, exhibit a higher frequency of mutations in human cancer." (PMID 38485987, 2024). "The analysis of KEGG pathways also revealed that the putative antihepatic cancer targets identified (Akt1, EGFR, TNF, and ALB) are involved in multiple pathways associated with cancer development and progression." (PMID 39502516, 2024). "Additional immunostaining experiments revealed the expression of β5‐integrin in cancer cells located around blood vessels within EGFR‐mutated tumors." (PMID 39435643, 2024). "These mutations lead to constitutive activation of the EGFR pathway, promoting uncontrolled cell growth and cancer development." (PMID 39130636, 2024). "We used target population characteristics including age, gender, initial cancer stage and type of EGFR mutation to generate the virtual populations for FLAURA, NEJ002 and AURA3 clinical trials." (PMID 38540317, 2024). "These advancements are tailored to attack specific cancer cells based on genetic markers, such as mutations in the epidermal growth factor receptor (EGFR), anaplastic lymphoma kinase (ALK), and c-ros oncogene 1 (ROS1) genes." (PMID 39044884, 2024). "In various cancers, the abnormal expression, mutation, or misregulation of EGFR is common, resulting in uncontrolled cellular proliferation." (PMID 38474160, 2024). "suggest that EV‐mediated transfer of wild‐type EGFR protein promotes osimertinib resistance to EGFR‐mutated sensitive cancer cells by activating PI3K/AKT and MAPK signaling pathways." (PMID 39611045, 2024). "Given the importance of MCL-1 proteolysis for apoptosis priming, prompt destruction of MCL-1 as an immediate response to anti-cancer treatment therefore underlies sensitivity to Osimertinib in EGFR mutant NSCLC." (PMID 39543744, 2024). "Since more than 90% of patients with HNSCC have overexpressed EGFR or random mutations, targeting this receptor is crucial for impeding cancer progression." (PMID 39035991, 2024). "The advent of clinically endorsed EGFR inhibitors has revolutionized the landscape of cancer treatment, yielding significant enhancements in both progression-free survival and overall survival among individuals afflicted with EGFR-mutated tumors." (PMID 38611728, 2024).